MMEL1 (membrane metalloendopeptidase like 1)
Description:
Metalloprotease involved in sperm function, possibly by modulating the processes of fertilization and early embryonic development. Degrades a broad variety of small peptides with a preference for peptides shorter than 3 kDa containing neutral bulky aliphatic or aromatic amino acid residues. Shares the same substrate specificity with MME and cleaves peptides at the same amide bond (By similarity).
Synonyms: NEPII; NEP2; NL2; MMEL2; SEP; NL1
Tractability: Antibody: UniProt places it where antibodies can reach, with medium confidence; UniProt predicts a signal peptide or a membrane-spanning region; its Gene Ontology location is reachable by antibodies, with medium confidence. PROTAC: ubiquitination databases record sites on it; a small molecule that binds it is known.
Target class: Enzyme; Hydrolase
Gene: Protein-coding gene on chromosome 1 (2,590,639 to 2,633,016, reverse strand). Ensembl gene ENSG00000142606.
Subcellular location: Membrane; Secreted
Gene Ontology:
Molecular function: endopeptidase activity; metalloendopeptidase activity; metallopeptidase activity
Biological process: proteolysis; protein processing
Cellular component: extracellular region; membrane; plasma membrane
Genetic constraint (gnomAD): Loss-of-function variants: 100 observed, 114.9 expected, observed/expected ratio (o/e) 0.87, 90% interval 0.74 to 1.03. The upper end of that interval is the gene's LOEUF score, 1.03, which puts it in group 4 of 6, group 1 being the genes least tolerant of losing a copy. Missense variants: 1,011 observed, 1,038.7 expected, observed/expected ratio (o/e) 0.97, 90% interval 0.92 to 1.02. Synonymous variants: 390 observed, 407.94 expected, observed/expected ratio (o/e) 0.96, 90% interval 0.88 to 1.04.
Homologues: Orthologues: chimpanzee MMEL1 (99% identical), macaque MMEL1 (97% identical), dog MMEL1 (86% identical), guinea pig MMEL1 (80% identical), pig MMEL1 (79% identical), rat Mmel1 (78% identical), mouse Mmel1 (77% identical), tropical clawed frog mmel1 (64% identical), zebrafish mmel1 (59% identical), Drosophila melanogaster Nep4 (38% identical), Drosophila melanogaster Nep3 (36% identical), Caenorhabditis elegans nep-1 (30% identical), and 19 more. Paralogues in human: MME (51% identical), ECE2 (37% identical), ECE1 (37% identical), PHEX (36% identical), ECEL1 (35% identical), KEL (24% identical).
Diseases named in the same sentence as MMEL1 in open-access papers:
MMEL1 is named in the same sentence as 21 diseases in open-access papers, as found by Europe PMC text mining. Sharing a sentence is not in itself a finding about the gene and the disease. The quoted sentences say what the papers report.
autoimmune disease (5 papers, 2010 to 2025). A disorder resulting from loss of function or tissue destruction of an organ or multiple organs, arising from humoral or cellular immune responses of the individual to their own tissue constituents. "Membrane metallo-endopeptidase-like (MMEL1 1) is most high ranked by Open Targets, also known as neprilysin 2, while MMEL1 is a membrane-bound metalloprotease that has been implicated in a range on autoimmune disease, including RA." (PMID 37498390, 2023). "Data from the current study extend that of previous work identifying that CTLA-4, the IL2_21 region, 6q23 (TNFAIP3), SH2B3, PRKCQ, MMEL1 and now TAGAP are susceptibility loci that are common to the three autoimmune diseases examined in the current study: T1D, CeD and RA." (PMID 20854658, 2010).
rheumatoid arthritis (5 papers, 2014 to 2025). A chronic, systemic autoimmune disorder characterized by inflammation in the synovial membranes and articular surfaces. "The recent GWAS and follow-up case-control studies have identified the association of MMEL1 gene with rheumatoid arthritis (RA) susceptibility." (PMID 26843707, 2015). "mir1286 down regulates C6orf15 and MMEL1; and alteration at these processes favor rheumatoid arthritis, and development and fertilization of ova." (PMID 24587348, 2014). "In our study, there were six novel loci outside of this region where genetic variation may influence rheumatoid arthritis risk via changes in DNA methylation (TTC34, MMEL1, AFF3, IRF5, CXCR5 and PGAP3)." (PMID 29893838, 2018).
multiple sclerosis (3 papers, 2014 to 2025). A progressive autoimmune disorder affecting the central nervous system resulting in demyelination. "Two multiple sclerosis (MS)-associated genetic regions were modeled; DRB1 (a Class II molecule of the major histocompatibility complex) and MMEL1 (an endopeptidase that degrades both neuropeptides and β-amyloid)." (PMID 24727690, 2014).
celiac disease (1 paper, 2015). An autoimmune genetic disorder with an unknown pattern of inheritance that primarily affects the digestive tract. "The principle finding was that rs3748816 in MMEL1 is a significant contributor to celiac disease susceptibility in patients of Saudi Arabian ancestry." (PMID 26843707, 2015). "However, further work involving reverse genetics is required to fully establish the function of this gene and to ascertain how the disease-causative polymorphism(s) in MMEL1 gene exert their effect in celiac disease biology." (PMID 26843707, 2015). "Although allele and genotype frequencies of IRAK1 and SH2B3 were insignificantly different between patients and controls, a potential synergistic effect was seen between MMEL1 and SH2B3 genes, reinforcing the significance of MMEL1 in celiac disease susceptibility." (PMID 26843707, 2015). "TNFRSF14 (rs2234167), a strong candidate for celiac diseases, which is less than 60 kb downstream is in strong linkage (r2 = 0.89) with rs3890745 of MMEL1 further raising the possibility of its indirect involvement in celiac disease." (PMID 26843707, 2015).
dementia (1 paper, 2025). Loss of intellectual abilities interfering with an individual's social and occupational functions. "This network is related to the pathogenesis of dementia by APLP1 and MMEL1, which help amyloid metabolism and neurodegeneration." (PMID 41032496, 2025).
hypothyroidism (1 paper, 2025). Abnormally low levels of thyroid hormone. "Among the genes identified, CCDC88B and MMEL1 were found to have positive associations with the risk of hypothyroidism (CCDC88B: OR = 1.004, p=4.69E − 07; MMEL1: OR = 1.004, p=6.65E − 06) and FinnGen cohorts (CCDC88B: OR = 1.044; MMEL1: OR = 1.038)." (PMID 40727246, 2025). "In summary, we found the correlation between the expression of CCDC88B, MMEL1, and hypothyroidism risk, which indicated potential drug targets for hypothyroidism." (PMID 40727246, 2025). "This suggested that the genes (CCDC88B and MMEL1) expression and hypothyroidism may share common causal variants, which could be potential drug targets for hypothyroidism." (PMID 40727246, 2025). "Finally, further study revealed CCDC88B and MMEL1 share a causal variant with hypothyroidism using MR and colocalization." (PMID 40727246, 2025). "Third, we identified CCDC88B and MMEL1 are potential drug targets for hypothyroidism, and experimental study and clinical trial should be performed to evaluate their therapeutic value." (PMID 40727246, 2025). "CCDC88B (rs11601860 on Chromosome 11) gene colocalized the association with hypothyroidism in whole blood (coloc.abf-PPH4 = 94.7%), and the MMEL1 (rs867436 on Chromosome 1) gene showed similar result of coloc.abf-PPH4 = 91.8%." (PMID 40727246, 2025). "We demonstrated causal association between PBC and hypothyroidism, and then further results revealed that CCDC88B and MMEL1 were two potential drug targets for hypothyroidism." (PMID 40727246, 2025). "So, it suggests that MMEL1 could be involved in the pathogenesis of hypothyroidism." (PMID 40727246, 2025).
osteoarthritis (1 paper, 2022). A noninflammatory degenerative joint disease occurring chiefly in older persons, characterized by degeneration of the articular cartilage, hypertrophy of bone at the margins and changes in the synovial membrane. "Genes annotated to these methylation sites are linked to osteoarthritis-relevant terms in cartilage, e.g., they encode a matrix metalloproteinase (MMEL1) or are involved in cell adhesion (CDH23 and PARVA)." (PMID 35679866, 2022).
MMEL1 also shares sentences with these, for which no sentence is quoted: Alzheimer disease (2 papers); infection (2); allergic rhinitis (1); asthma (1); autoimmune thyroid disease (1); eczema (1); glioblastoma (1); mood disorder (1); neurodegenerative disease (1); nosocomial infection (1); retinal degeneration (1); sarcoma (1); tumour (1); unipolar depression (1).